CTRB1 (chymotrypsinogen B1)
Synonyms: CTRB
Tractability: Small molecule: a high-quality ligand is known; it belongs to a druggable protein family. Antibody: its Gene Ontology location is reachable by antibodies, with high confidence; UniProt places it where antibodies can reach, with medium confidence; UniProt predicts a signal peptide or a membrane-spanning region. PROTAC: a small molecule that binds it is known.
Target class: Serine protease; Enzyme; Serine protease PA clan; Serine protease S1A subfamily; Protease
Gene: Protein-coding gene on chromosome 16 (75,218,988 to 75,226,338, forward strand). Ensembl gene ENSG00000168925.
Subcellular location: Secreted, extracellular space
Pathways (Reactome):
Extracellular matrix organization: Activation of Matrix Metalloproteinases
Metabolism: Uptake of dietary cobalamins into enterocytes
Gene Ontology:
Molecular function: protein binding; serine-type endopeptidase activity
Biological process: proteolysis
Cellular component: extracellular region
Genetic constraint (gnomAD): Loss-of-function variants: 10 observed, 7.35 expected, observed/expected ratio (o/e) 1.36, 90% interval 0.82 to 1.9. That is too few expected variants to judge how well the gene tolerates losing a copy. Missense variants: 168 observed, 123.32 expected, observed/expected ratio (o/e) 1.36, 90% interval 1.2 to 1.55. Synonymous variants: 68 observed, 51.89 expected, observed/expected ratio (o/e) 1.31, 90% interval 1.08 to 1.6.
Homologues: Orthologues: mouse Ctrb1 (85% identical), rat Ctrb1 (81% identical), macaque CTRB2 (79% identical), zebrafish ctrb.2 (68% identical), chimpanzee CTRB2 (66% identical), zebrafish ctrb.1 (66% identical), tropical clawed frog ctrb1 (65% identical), zebrafish ctrb.3 (65% identical), Drosophila melanogaster CG11912 (33% identical). Paralogues in human: CTRB2 (96% identical), CTRC (40% identical).
Diseases named in the same sentence as CTRB1 in open-access papers:
CTRB1 is named in the same sentence as 18 diseases in open-access papers, as found by Europe PMC text mining. Sharing a sentence is not in itself a finding about the gene and the disease. The quoted sentences say what the papers report.
pancreatitis (5 papers, 2008 to 2025). Inflammation of the pancreas. "The intronic variant rs8051363 in CTRB1 was associated with both amylase and lipase, clinical assays of pancreas function used to diagnose pancreatitis." (PMID 33175840, 2020). "Accordingly, in laboratory mouse models, CTRB1 mediates protection against pancreatitis through cleavage of mouse anionic (T8 and T9) and cationic (T7) trypsinogen while CTRL plays a minor role." (PMID 40133496, 2025). "We investigated the expression of pancreatitis-associated genes with the ability to act as positive regulators of the IL-6 amplifier; these genes include GGT1, PRSS1, CASR, CTRB1, ABO, SPINK1, and CTRC." (PMID 38806529, 2024). "Even though CTRB1 and CTRB2 together are the most abundant chymotrypsins in humans, there are no reported mutations in these proteases in association with pancreatitis." (PMID 32678161, 2020). "Thus, relative to CTRC, the contribution of CTRB1 and CTRB2 to the chymotrypsin-dependent protection against pancreatitis in humans seems limited." (PMID 32678161, 2020). "In contrast to the demonstrated protective effects of CTRB1 and CTRC in mice against pancreatitis, the observations reported here did not indicate a similar role for CTRL." (PMID 32678161, 2020).
type 2 diabetes (5 papers, 2016 to 2024). "A recent analysis suggested that the same genetic variant alters risk of both type 1 and type 2 diabetes in five regions, near CENPW, CTRB1/BCAR1, GLIS3, BCL11A and THADA." (PMID 33830302, 2021). "This SNP on chromosome 16q23.1 has been identified as a risk factor for type 1 diabetes and as a protective factor for type 2 diabetes, and increase gene expression of CTRB1/2 in islets and pancreata and enzyme activity in stool, implicating a key role of the enteroendocrine system." (PMID 27139004, 2016). "For the BCAR1/CTRB1/CTRB2 region, the scores were negatively correlated (r = − 0.20), consistent with studies showing that the G allele of the rs720877 SNP in this region is associated with increased risk of type 1 diabetes but with decreased risk of type 2 diabetes." (PMID 31438962, 2019).
diabetes (4 papers, 2020 to 2025). "ChIP-seq analysis in primary mouse islets confirmed CREB binding in active enhancers in Med14 S983 dependent diabetes-associated loci Bcar1/Ctrb1 and Peak1/Hmg20a." (PMID 40667025, 2025). "CTRB1, which encodes chymotrypsinogen via incretin pathway, has been shown to be associated with the development of diabetes and response to DPP-4 inhibitor treatment." (PMID 38027148, 2023). "Among them, 89 upregulated and 24 downregulated DEGs were found to be associated with diabetes progression (e.g., Ctrb1, Cpa2, and Insig1) and diabetes (e.g., Car3, Dio1, and Mup5), respectively." (PMID 33329383, 2020). "Finally, the Mendelian randomization phenome-wide association study corroborated MANSC4 as a reliable target capable of mitigating the risk of various forms of diabetes, and it revealed the absence of adverse effects linked to CTRB1, SIGLEC5 and MST1." (PMID 38931433, 2024).
type 1 diabetes (4 papers, 2016 to 2025). "We show colocalization of pQTLs for CTRB1, APOBR, IL7R, CPA1, and PNLIPRP1 with Type 1 diabetes GWAS signals, and Mendelian randomization causally implicates each of these five proteins in the aetiology of Type 1 diabetes." (PMID 40263317, 2025).
pancreatic cancer (3 papers, 2008 to 2024). "One example is CTRB1, which is a serine protease digestive enzyme precursor produced largely by the exocrine pancreas and which was associated with a lower risk of pancreatic cancer in two independent cancer GWAS." (PMID 38684708, 2024). "Here we find 40 proteins associated with common cancers, such as PLAUR and risk of breast cancer [odds ratio per standard deviation increment: 2.27, 1.88-2.74], and with high-mortality cancers, such as CTRB1 and pancreatic cancer [0.79, 0.73-0.85]." (PMID 38684708, 2024). "Therefore, further analyses are needed to clarify the role of the CTRB1-CTRB2 locus in pancreatic cancer risk, which could include pre-clinical assessment of CTRB1 and CTRB2 as potential anti-tumour agents as was previously conducted for pro-enzymes PRSS1 and Chymotrypsinogen A28." (PMID 38684708, 2024). "CTRB1 and ABO were associated with risk of pancreatic cancer of which one was only associated with pancreas cancer and largely only expressed in the exocrine pancreas, CTRB1 [OR: 0.79, 95% CI: 0.73 to 0.85; PP4: 0.99]." (PMID 38684708, 2024).
pancreas cancer (2 papers, 2008 to 2024). "Additionally, replication in UKBB and Finngen was observed for other results, including PLAUR [breast cancer OR: 1.82, 95% CI: 1.37 to 2.42], POGLUT3 [kidney cancer OR: 0.72, 95% CI: 0.60 to 0.88], and CTRB1 [pancreas cancer OR: 0.83, 95% CI: 0.75 to 0.92]." (PMID 38684708, 2024).
coronary artery disease (1 paper, 2019). "Two novel loci were associated with birthweight and adult coronary artery disease (rs2870463 in CTRB1) and with birthweight and adult waist circumference (rs12704673 in CALCR)." (PMID 30858448, 2019). "In our study, rs2870463 G in CTRB1 gene was associated with decreased birthweight and increased risk of coronary artery disease with posterior probability (PP) = 0.951 and rs12704673 T in CALCR gene was associated with increased birthweight and increased waist circumference with PP = 0.962." (PMID 30858448, 2019). "It is noteworthy that rs2870463 G near CTRB1 and BCAR1 was found to be significantly associated with decreased birthweight and higher risk of coronary artery disease." (PMID 30858448, 2019).
COVID-19 (1 paper, 2023). A disease caused by infection with severe acute respiratory syndrome coronavirus 2. "Our results showed that low levels of DDX55, ANXA1, PICAL, and AGRG6 before treatment, as well as elevated levels of CTRB1 pre-MSC treatment, were biomarkers for predicting response to MSC therapy in severe COVID-19 patients." (PMID 38072927, 2023). "Finally, multivariate logistic regression identified AGRG6, PICAL, CTRB1, and ANXA1 as independent factors that predicted response to MSC therapy in patients with severe COVID-19." (PMID 38072927, 2023).
lung diseases (1 paper, 2023). "At present, studies on CTRB1 are mainly focused on pancreas-related diseases, and its role in lung diseases needs to be further explored." (PMID 38072927, 2023).
tumor (6 papers, 2012 to 2024). "In all tumor tissues, TAMs replaced resident populations such as lung alveolar macrophages, prostate CTRB1+ macrophages, and renal GPX3+ macrophages." (PMID 38424167, 2024). "According to the immunohistochemical staining of normal cell-specific genes CTRB1 and REG1A, these cells showed rather gathered patterns adjacent to cancer cells within the tumor lesions, and their distributions varied between different patients." (PMID 35165277, 2022). "Therefore, all MRM results demonstrated that the serum abundance of the six proteins, CELA1, CEL2A, chymopasin, CTRB1, TRY2, and TRY4, reflected tumor development and served as CRC serum biomarkers in this mouse model." (PMID 27081040, 2016).
infection (1 paper, 2018). The state of being infected such as from the introduction of a foreign agent such as serum, vaccine, antigenic substance or organism. "Increasing hLRH-1 dosage by AAV-mediated infection caused an upregulation of the LRH-1 target Ctrb1." (PMID 30305617, 2018).
CTRB1 also shares sentences with these, for which no sentence is quoted: cancer (4 papers); acute pancreatitis (1); breast carcinoma (1); colorectal cancer (1); glioma (1); kidney cancer (1); pancreatic insufficiency (1).